EGFR (epidermal growth factor receptor)
Diseases named in the same sentence as EGFR in open-access papers (continued):
Sharing a sentence is not in itself a finding about the gene and the disease.
breast carcinoma (continued). "From gene expression and functional analysis studies, cyclooxygenase COX2, Epidermal Growth Factor Receptor (EGFR) ligand HBEGF, and alpha-2,6-sialyltransferase ST6GALNAC5 have all been identified as mediators of breast cancer cell extravasation into the brain." (PMID 32613208, 2020). "Epidermal growth factor receptor (EGFR) is altered in triple-negative breast cancer (TNBC), however, there are currently no EGFR targeting therapies approved for the treatment of breast cancer." (PMID 32577155, 2020). "However, by incorporating anti-EGFR aptamer, our results suggest that the 4WJ-X-24 PTXs-EGFRapt nanoparticles can specifically bind to MDA-MB-231 breast cancer cells." (PMID 32080195, 2020). "Also similar to TamR breast cancer cells, MCF7-BP1 and T47D-BP1 were resistant to tamoxifen treatment, had elevated epidermal growth factor receptor (EGFR) expression, increased phospho-EGFR (pEGFR), and phospho-Erk (pErk)." (PMID 32435229, 2020). "Three of the proteins identified as HUNK substrates; EGFR, Run domain Beclin-1-interacting and cysteine-rich domain-containing protein (RUBICON), and integral membrane protein 2A (ITM2A), are described in the context of breast cancer." (PMID 32676513, 2020). "One of the first studies engineering exosomes with miRNAs for treatment purposes loaded miR-let7a inside GE11 peptide-positive cells, a modification designed to target epidermal growth factor receptor (EGFR)-positive cells, expressed in a high variety of tumors such as in breast cancer." (PMID 33374908, 2020). "Moreover, additional markers identified include EGFR, AP-1, p63, and TGF-β, as their pro-oncogenic functions regulate breast cancer invasiveness, and therefore, these can be exploited as therapeutic targets in breast cancer." (PMID 33092068, 2020). "In addition, the model of drug response in the genome was also demonstrated at the proteomic level (for example, EXP(EGFR) is sensitive to AZD6244 at both protein and gene levels for breast cancer)." (PMID 32916316, 2020). "Cetuximab-SB-Saporin, targeting the human epidermal growth factor receptor (EGFR), caused a concentration-dependent decrease in cell viability of EGFR-high MDA-MB-468, but not of EGFR-low CAL51, breast cancer cells." (PMID 32483228, 2020). "Moreover, combining gefitinib (EGFR inhibitor) and PD98059 (MEK inhibitor) resulted in synergistic induction of cell death in breast cancer cells." (PMID 33021054, 2020). "A novel finding in the present study is that the partial and mesenchymal EMT phenotypes displayed a high fraction of EGFR and PDGFC positivity compared with the epithelial and negative phenotypes, further supporting that these phenotypes define an aggressive type of breast cancer." (PMID 32300922, 2020). "The anti-tumour effect of dual BET/EGFR inhibition is also significant in a series of other types of cancer, including luminal/HER2+ breast cancer, gastric cancer, pancreatic cancer, ovarian cancer and chronic myelogenous leukaemia, reflecting its great potential value in cancer treatment." (PMID 31937753, 2020). "Indeed, ARF6 plays a role in EGFR-driven tumorigenesis, where it acts downstream of EGFR and GEP100 to induce invasion and malignancy in breast cancer, EMT in head and neck squamous cell carcinoma (HNSCC) and invasion and prognosis in NSCLC." (PMID 33302515, 2020). "The combination of EGFR-CAR NK-92 cells with oHSV-1 resulted in more efficient killing of breast cancer tumor cells engrafted into the brain compared to monotherapies and significantly improved survival of mice bearing breast cancer tumor cells in the brain." (PMID 33287875, 2020). "Additionally, KLF8 directly induces EGFR gene expression and activates the MEK/ERK pathway in breast cancer to promote invasion and proliferation." (PMID 32552913, 2020). "Therefore, exclusive interaction of CFIm25/CPSF1 complex with distal region of EGFR and AKT3 3′-UTR coding mRNA, would guarantee suppression of breast cancer progression." (PMID 32665581, 2020).
breast carcinoma (continued). "The EGFR/ERK1/2 signaling cascade upregulates the expression of Egr-1 that in turn participates in the transcription of CTGF and cyclin D1, two genes that regulate breast cancer growth." (PMID 33117280, 2020). "Clinical support and evidence to guide management are absent for patients with breast cancer coexisting with HER-2 amplification and EGFR mutations." (PMID 32547945, 2020). "Taken together, these results indicate that CD99-derived agonist ligand inhibits epidermal growth factor (EGF)-induced EGFR dimerization through impairment of cytoskeletal reorganization by PTPN12-dependent c-Src/FAK inactivation, thereby suppressing breast cancer growth." (PMID 33050232, 2020). "Following treatment with trastuzumab or a dual epidermal growth factor receptor (EGFR)/ErbB2 tyrosine kinase inhibitor (TKI; i.e., lapatanib), in a range of HER2 positive breast cancer cell lines, HER2 was downregulated, while the Notch activity was upregulated." (PMID 32575680, 2020). "Moreover, by enhancing the levels of EGFR, HB-EGF, JUN and, in particular, FOS family members, ΔNp63 can promote the pro-oncogenic transcriptional program of SMAD and AP-1 in breast cancer cells." (PMID 32350443, 2020). "Moreover, the survival of breast cancer patients with high phosphorylated HER2 or both HER2 and EGFR proteins is significantly shortened." (PMID 32517369, 2020). "The authors demonstrated that CL-4RNV616 binds and inhibits EGFR, has high stability in human serum, and increases apoptosis in cancer cells; in breast cancer, biopsy-based immunostaining demonstrated high EGFR, but no data were given on GBM tissues." (PMID 32764266, 2020). "EGFR is a tyrosine kinase, often mutated, overexpressed and acting as a promoter of tumorigenesis in epithelial tumors, such as lung, breast cancer and glioblastoma; however, the role of EGFR in GIST is not that well-investigated and yet controversial." (PMID 32708220, 2020). "Previous studies have shown that estrogen receptor (ER) and progesterone receptor (PR) positives are higher in geriatric breast cancer (GBC), with less overexpression of epidermal growth factor receptor (EGFR), human epidermal growth factor receptor 2 (HER2), and ki67." (PMID 32079071, 2020). "Our studies show for the first time, that besides affecting the immunogenic potential of breast cancer cells, MH also impacts EGFR expression, again independent of temperature, way of heating, RT fractionation, and time." (PMID 32349284, 2020). "Elevated levels of resistin and epidermal growth factor receptor (EGFR) facilitate the development of breast cancer, although there are no reports of any correlation between these proteins." (PMID 33313320, 2020). "Mechanisms of synergism between YM155 and EGFR inhibitors such as afatinib have not yet been extensively explored in breast cancer." (PMID 32001757, 2020). "For example, in human breast cancer, autophagy induction is enhanced via cell growth suppression by integral membrane protein 2A PAQR3 inhibits tumor progression in NSCLC cells by modulating EGFR-regulated autophagy." (PMID 33381557, 2020). "Moreover, EGFR has been reported to interact with AHR and GPER (G protein estrogen receptor) to stimulate breast cancer progression and EGFR can bypass RhoA to activate YAP signaling to promote hepatocellular carcinoma proliferation." (PMID 32546278, 2020). "Clinical trials of EGFR-targeted therapy for breast cancer patients have not shown clear clinical benefits." (PMID 32883032, 2020). "THZ1 had synergistic or additive effects when combined with the EGFR inhibitor erlotinib, with no outward selectivity for a particular subtype of breast cancer." (PMID 32155786, 2020). "Belonging to the Epidermal Growth Factor Receptor (EGF/EGFR) family, the ERBB2/Human Epidermal Growth Factor Receptor 2 (HER2) receptor signaling pathway has a well-documented role in driving aggressive, metastatic breast cancers when aberrantly activated." (PMID 33172038, 2020).
breast carcinoma (continued). "In the EGFR+ HCC1937 cells, and also in basal-like EGFR+ and HER2+ HCC1954 breast cancer cells, the presence of EGF strongly enhanced both the basal and TGFβ-induced levels of subsets of these invasion genes, whereas HER2+ HCC202 cells showed similar result as MII cells." (PMID 32350443, 2020). "Interestingly, PRMT1 knockdown was also correlated with decreased EGFR activity and suppressed proliferation of in MDA-MB-468 breast cancer cells that are derived from an African American breast cancer patient." (PMID 32873298, 2020). "In addition, although lapatinib is a dual EGFR/HER2 inhibitor, the EGFR signaling is expected to have little contribution to proliferative activities in HER2+ breast cancer cells." (PMID 33303839, 2020). "For example, breast cancer cells or mammary epithelial cells over-expressing ERBB2 were more sensitive to the tumor promoting effects of alcohol which suggests that oxidative stress and EGFR/ ERBB2 signaling play an important role in this process." (PMID 33203443, 2020). "Moreover, a dis-localisation of EGFR and alteration of AKT signalling pathway that initiates the pro-apoptotic process were observed in human breast cancer cell lines MCF-7, T47D and MDA-MB-231 following the treatment of EPA and DHA." (PMID 33287803, 2020). "CDK4/6 inhibitors (i.e., abemaciclib, palbociclib, and ribociclib) were recently approved for hormone receptor positive, human epidermal growth factor receptor 2 (EGFR)-negative, advanced breast cancer in combination with hormone therapy." (PMID 32373071, 2020). "Basal-like breast cancer (BLBC) is a distinct pathological subtype that is characterized by expression of cytokeratin (including CK5/6, CK14, CK17, and etc.)and/or human epidermal growth factor receptor (EGFR)." (PMID 33552956, 2020). "Interestingly, AGO2 expression has been shown to be regulated by the epidermal growth factor receptor (EGFR) and mitogen-activated protein kinase (MAPK) pathways in breast cancer cell lines." (PMID 32646059, 2020). "In this study, both resistin and EGFR impacted adversely upon survival in breast cancer, but neither protein alone had a significant impact." (PMID 33313320, 2020). "Similarly, in the basal-like breast cancer cell line—MDA-MB-468—and in the DTC cell line from the bone marrow—BC-M1—the induction of the EGFR protein was observed." (PMID 32466213, 2020). "However, no studies have been conducted to examine a relationship between EGFR and HUNK in breast cancer metastasis." (PMID 31597954, 2020). "Furthermore, the Michael acceptor, neratinib, a dual inhibitor of the human epidermal growth factor receptor 2 and epidermal growth factor receptor, was recently approved by the FDA (2017) and by the EMA (2018) for the treatment of breast cancer." (PMID 33013366, 2020). "Thus, we used SKBR3 breast cancer cell line, in which HER2-activated RASWT-GTP levels are attenuated by Lapatinib (dual EGFR/HER2 tyrosine kinase inhibitor) treatment." (PMID 32873792, 2020). "We overexpressed MGAT3 in breast cancer MDA-MB-231 cells, and overexpression of MGAT3 significantly enhanced the bisecting N-GlcNAc on EGFR and suppressed the EGFR/Erk signaling, which further resulted in the reduction of migratory ability, cell proliferation, and clonal formation." (PMID 32612952, 2020). "In addition to breast cancer, HER2 overexpression exists in many other cancer types, for instance in bladder cancer, where co-overexpression of HER2 and EGFR was reported for the majority of the tumors and metastases." (PMID 33260837, 2020). "Both 111In- and 177Lu-labelled bsRICs were also effective for treatment of TrR1 human breast cancer xenografts that are HER2 and EGFR-positive, but have acquired resistance to trastuzumab, but these tumours were less sensitive than MDA-MB-231/H2N tumour xenografts." (PMID 31659527, 2019). "The results indicated that ESR1, PGR, EGFR, PTGS2, and Src may be the potential therapeutic target of RYNXC for the treatment of breast cancer." (PMID 30906412, 2019).
breast carcinoma (continued). "In breast cancer cell lines, MYOF forms a complex with EGFR to induce EGFR recycling." (PMID 31477752, 2019). "In addition, intrinsic kinases such as EGFR (epidermal growth factor receptor) and VEGFR (vascular endothelial growth factor receptor) can mediate aberrant phosphorylation of STAT3 in breast cancer." (PMID 31058868, 2019). "Additionally, this phosphatase has been shown to have tumor-suppressive roles by inactivating epidermal growth factor receptor (EGFR) and platelet derived growth factor receptor (PDGFRβ) signaling in breast cancer, and Ras signaling in colorectal cancer." (PMID 31756921, 2019). "Membrane raft fractions were found to contain more protein levels of EGFR than non-membrane raft fractions in cancer cells, such as cervical, colon and breast cancer cells." (PMID 31477154, 2019). "Overall, these results showed that EGFR and EGF could inhibit the expression of AJAP1 and promot the β-catenin nuclear localization in the breast cancer cell lines." (PMID 31171012, 2019). "This structure also included CD19 and CD20 for B cell leukemia and lymphoma, CD138 for myeloma, human epidermal growth factor receptor 2 (HER2) and epidermal growth factor receptor for brain metastasis, HER2 and EGFR for breast cancer, and GD2 for neuroblastoma." (PMID 30646574, 2019). "Although the sample number is small, there is a very significant negative correlation (r = −0.56) between CGRRF1 and EGFR protein levels in the breast cancer cell lines." (PMID 31801577, 2019). "However, our study explored and validated that EGFR also can inhibit AJAP1 expression and β-catenin activity in breast cancer cells." (PMID 31171012, 2019). "In summary, dual HER2 and EGFR inhibitors exhibit modest CNS activity and may be used in the management of HER2-positive breast cancer BM." (PMID 31803366, 2019). "In this study, we analyzed the cytotoxic effect of PTX and LAP on MCF-7 breast cancer cells, which are characterized by the absence of EGFR and HER-2 receptors." (PMID 30959904, 2019). "Therefore, the more the alkyl chain CH3(CH2)n occupies the hydrophobic allosteric pocket, the greater the EGFR degradation is, which correlates with increased detachment of cancer cells from the ECM and toxicity of compounds in breast cancer cells." (PMID 31374910, 2019). "The mechanism may be that epidermal growth factor receptor (EGFR) is activated by guanosine triphosphatases (GTPases) Rac1 and Cdc42 to accelerate cell cycle progression and promote breast cancer cell proliferation." (PMID 31337431, 2019). "By comparing the TReD results with the gene expression profiles, we found a clear negative correlation between the EGFR diffusivities and the breast cancer luminal differentiation scores (r = −0.75)." (PMID 30833579, 2019). "An inverse relationship between ER activity and EGFR and HER2 expression has been reported in clinical breast cancer, with overexpression of these receptor tyrosine kinases being associated with decreased sensitivity to endocrine therapy and a poorer prognosis." (PMID 30987655, 2019). "In contrast, pathway models trained with CCLE data successfully identified a few top pathways involving both ERBB2 and EGFR, including “anti-apoptotic action of ErbB2 in breast cancer”, “ERBB family signaling”, “mitogenic action of ErbB2 in breast cancer” and “EGFR signalling via small GTPase”." (PMID 30704449, 2019). "In contrast to HER2-negative breast cancer, HER2-positive breast cancer expresses higher levels of EGFR and exhibits increased signaling from HER family receptors, such as EGFR, as well as EGFR/HER2 crosstalk." (PMID 30736768, 2019). "Furthermore, we showed that EGFR was differentially expressed in other cells lines such as NSCLC cells, breast cancer, and pancreatic cancer cells." (PMID 30372581, 2019). "NLS peptide modification enhanced nuclear uptake 2-fold in EGFR-positive MDA-MB-468 human breast cancer cells compared to 111In-nimotuzumab without NLS." (PMID 31659527, 2019).
breast carcinoma (continued). "OA can activate EGFR signaling in endothelial cells and in MCF-7 breast cancer cells, yet it does not appear to affect EGFR tyrosine phosphorylation in MDA-MB-231 breast cancer cells." (PMID 31069012, 2019). "This research provided novel findings demonstrating that the combination of the inhibitor of EGFR and the AJAP1 inducer may be beneficial to breast cancer prognosis." (PMID 31171012, 2019). "The activity of ATX-101 is not specific for the 67NR cells as ATX-101 also enhanced the effect of AEE788 in three other human cancer cell lines overexpressing EGFR; the human colon cancer cell line SW480, the human bladder cancer cell line 5637 and the human breast cancer cell line MDA-468." (PMID 31921382, 2019). "Moreover, pharmacological FGFR4 inhibition specifically sensitized the HER2+ MDA-MB-453 breast cancer cells, not only to HER2/EGFR and AKT/mTOR inhibitors, but also to clinically relevant apoptosis modulators." (PMID 30903103, 2019). "Furthermore, GTN inhibited metastasized breast cancer cells (in the detachment model) by inducing anoikis via decreased MMP secretion, a reversal of the EMT proteins, and attenuated EGFR/FAK/Src survival pathways." (PMID 31416203, 2019). "Studies have indicated that miR-133b can regulate oncogenic transcripts of gastric, esophageal, or breast cancer by targeting Fascin Actin-Bundling Protein 1(FSCIN1)/Sp1, the epidermal growth factor receptor (EGFR) and SRY-Box Transcription Factor 9 (SOX9), respectively." (PMID 31771219, 2019). "Furthermore, the downregulation of c-Src/EGFR-mediated signaling is involved in honokiol-induced cell cycle arrest and apoptosis in MDA-MB-231 human breast cancer cells." (PMID 31877856, 2019). "In this study, we screened out a non-classical PKCδ/MAPK/ERK signaling pathway involved in EGF-induced PN-1 up-regulation in breast cancer cells, first provided the evidence that PN-1 could be up-regulated by EGF/EGFR/PKCδ/MEK/ERK signaling pathway." (PMID 31501409, 2019). "Lapatinib, known as a small-molecule kinase inhibitor, could target the EGFR gene and Erb-B2 Receptor Tyrosine Kinase 2 (ERBB2) gene, which was approved by the US Food and Drug Administration (FDA) in 2007 for the therapy of breast cancer patients." (PMID 31265947, 2019). "Given the current limitations of EGFR and HER2-targeted drugs in treating breast cancer, new agents that act through a synthetic lethal mechanism could benefit patients with EGFR+ TNBCs and drug- resistant HER2+ tumors." (PMID 31839995, 2019). "Some reports support that genistein does not inhibit EGFR phosphorylation in breast cancer or prostate cancer cells following stimulation with EGF." (PMID 31100782, 2019). "It blocks EGFR-controlled VEGF formation and inhibits cancer angiogenesis in breast cancer." (PMID 30871059, 2019). "To investigate whether Sp1 and Smad3 elicit a synergetic effect on TGF‐β‐induced upregulation of EGFR expression, on the basis of Smad3 knockdown, we used the Sp1 inhibitor MTM to treat breast cancer cells." (PMID 29215776, 2018). "Therefore, upregulation of normal Ras activity by RTKs, such as the EGFR and insulin growth factor receptor (IGF1-R), has been shown in ERα positive breast cancer." (PMID 30208932, 2018). "Inhibiting any of a dozen different oncogenic pathway components, including EGFR, PI3K and MMP-9, could revert breast cancer cells." (PMID 29560860, 2018). "Moreover, Rg3-induced apoptosis in A549 lung adenocarcinoma via downregulation of epidermal growth factor receptor and in human breast cancer (MDA-MB-231) cells, thus preventing breast cancer." (PMID 30405742, 2018). "For instance, EGFR and Her2 signaling have been shown to increase the rate of HIF-1α synthesis and the subsequent expression of survivin and VEGF in breast cancer cells, through the involvement of the PI3k/AKT pathway and the downstream kinase FRAP (FKBP-rapamycin-associated protein)." (PMID 29996493, 2018).